WT1 (WT1 transcription factor)
Diseases named in the same sentence as WT1 in open-access papers (continued):
Sharing a sentence is not in itself a finding about the gene and the disease.
tumor (continued). "The results demonstrated that the novel and chemically synthesized antagonistic peptide WIP2W can specifically bind to the intracellular WT1 protein, and its micellar formulation (M—WIP2W) can significantly enhance cell death and inhibit the tumor growth of WT1+ BP-CML mice." (PMID 37765274, 2023). "In cases where DTH values are continuously increased with WT1-DC therapy, it is thought that the activation of anti-tumor immunity is occurring along with the improvement of IPS, increasing the possibility of prolonged overall survival even in late-stage cancer." (PMID 38143707, 2023). "These WT1-specific B cells are activated by the administered WT1 Trio and may affect clinical outcomes through antigen presentation or immunomodulation of the tumor immune microenvironment via cytokine production and release." (PMID 36672344, 2023). "Additionally, WIP2W and M—WIP2W treatment significantly diminished WT1 protein levels in the tumor tissues relative to controls, underscoring WIP2W’s antagonistic effect." (PMID 37765274, 2023). "The vaccine successfully triggered and sustained CD4+ T cell help-enhanced immune responses in the intestinal tract, and then in systemic circulation and the spleen, thus allowing WT1-specific T cells to reach the tumor where they exerted obvious antitumor activity." (PMID 36803483, 2023). "The secreted ESK1 BiTE recruited and redirected other T cells to WT1 on the tumor cells." (PMID 37214945, 2023). "Recently, Wilms’ tumour 1 (WT1) has emerged as a histological tumour marker." (PMID 37296736, 2023). "In line with these in vitro results, xenografted tumours formed by miR-498-5p-overexpressing H1299 cells showed reduced tumorigenic potential compared with those formed by control cells, while WT1 overexpression showed enhanced tumour promoting capacity in nude mice." (PMID 37667197, 2023). "In addition, the group with WT1-332-specific IL-10 released from PBMCs tended to have a lower completion rate and a higher rate of tumor progression." (PMID 36672344, 2023). "In this study, we hypothesized that WT1 exerted tumour promoting effects in NSCLC and was targeted by miR-498-5p." (PMID 37667197, 2023). "This raises the possibility of migration of many activated WT1-235-specific immune cells from peripheral blood to the tumor site, which ultimately could have led to a decrease in WT1-235-specific cellular immune responses in PBMCs." (PMID 36672344, 2023). "WT1 was originally considered a tumor suppressor gene, repressing the transcription of several growth factors and growth factor receptors including insulin-like growth factor II, insulin-like growth factor receptor, PDGF, TGF β1, PAX2, retinoic acid receptor α and EGR1." (PMID 36818371, 2022). "This indicated that WT1 antigen-specific CD8+ T cells correlated with tumor reduction." (PMID 40977909, 2022). "Interestingly, one of the positive cases, which was labeled +1, showed only two tumor cells with nuclear staining for WT1, with weak and moderate intensity, respectively." (PMID 35453662, 2022). "WT1 CAR T cells have also exhibited the ability to lyse WT1 primary tumor cells." (PMID 35740430, 2022). "On the other hand, WT1 is expressed in a wide range of adult tumor subtypes of epithelial, mesenchymal, hematopoietic and neuronal origin, without being expressed in the corresponding healthy tissue, thus mandating the proposition that WT1 functions as an oncogene in these situations." (PMID 35453662, 2022). "The occurrence of the tumor in both twin sisters, the early age of onset, and the identical histology of the tumors may suggest the involvement of genetic factors, such as the WT1 gene, in the etiology of the disease in our girls." (PMID 35205416, 2022). "In addition, in vivo experiments have shown that Wt1 deletion in tumors significantly suppresses blood vessel and tumor formation." (PMID 36233262, 2022). "Initial research into the role of WT1 in tumors has focused on hematological-derived tumor cells." (PMID 35915803, 2022).
tumor (continued). "Thus, we found it necessary to elaborate this study, which is, currently, to the best of our knowledge, the largest aRCC-dedicated tumor tissue WT1 protein expression analysis." (PMID 35453662, 2022). "A T cell response against the WT1 protein was evoked, and WT1-expressing tumor cells were killed." (PMID 35328721, 2022). "In contrast, in the current investigation, we report the highest percentage of exclusively nuclear WT1-positive aRCC tumor cells to date (12.5%), with a much lower rate (5.35%) of cases showing isolated endothelial WT1 nuclear immunoreactivity of intratumoral blood vessels." (PMID 35453662, 2022). "In addition, Wt1 coexpression with markers of endothelial cells, hematopoietic progenitor cells, myeloid cells, and pericytes has been observed in human tumor samples, supporting a high Wt1 contribution to the tumor stroma." (PMID 36233262, 2022). "The WT1 protein is responsible for many processes that promote oncological development, including cancer cell growth, resistance to apoptosis, cell migration, and tumor vascularization." (PMID 35565190, 2022). "In contrast, some studies have shown that WT1 can inhibit tumor growth." (PMID 35915803, 2022). "WT1 is a tumor suppressor that contains four zinc finger DNA binding domains." (PMID 35379887, 2022). "The results suggest that WT1 acts as a tumor suppressor in human RCC cells." (PMID 35915803, 2022). "More recent studies depicted that WT1 manifests both tumor suppressor and oncogenic properties." (PMID 36818371, 2022). "Interestingly, previous studies and STRING analysis indicate that PDPN expression was coordinated with the expression of other tumor promoters, specifically Kdr/Vegfr2 and Wt1, that were induced by oncogenic Src kinase activity." (PMID 35177067, 2022). "The WT1 gene was cloned in 1990 and it was originally described as a classic tumor suppressor gene." (PMID 34692659, 2021). "Taken together, these data suggest that therapeutic targeting of WT1 in PCa could be beneficial for tumor growth inhibition." (PMID 34504167, 2021). "WT1 acts either as a tumour suppressor or oncogene depending on the cellular context and PPIs." (PMID 33395407, 2021). "The present study was the first report clearly demonstrating the striking different mechanisms in anticancer immunity between TAA peptide-based vaccines such as WT1 peptide vaccine and immune checkpoint inhibitors such as anti-PD-1 antibody for the same tumor under the same microenvironment." (PMID 34355173, 2021). "Immunohistochemical analyses revealed these tumor cells to be positive for WT1." (PMID 35187045, 2021). "It has been shown that in KRAS-dependent tumors, inactivation of WT1 will reduce tumor formation." (PMID 34615983, 2021). "In addition to the requisite role of WT1 in development, it also plays a complex role in tumorigenesis, acting as either a tumor suppressor or an oncogene depending on the cellular context." (PMID 34504167, 2021). "Importantly, the number of CD4+ and CD8+ T cells and NK cells per one unit of tumor cell-emitting bioluminescence was also statistically significantly higher in WT1 peptide vaccine-treated mice than anti-PD-1 antibody-treated and control mice." (PMID 34355173, 2021). "Notably, the expression of WT1 and cyclin D1 was also retained in those cases in which the conventional tumor markers (myogenin, desmin and MyoD1 for RMS; CD99 for EWS; NB84 for NB) were focally expressed or more rarely absent." (PMID 34943491, 2021). "As far as breast cancer cells are concerned, WT1 may influence tumor cell growth by regulating the destabilization of β-catenin." (PMID 34692659, 2021). "The tumor-infiltrating CD3+ CD8+ T cells were stained with WT1-tetramer antibody." (PMID 34355173, 2021). "Furthermore, to examine the frequencies of tumor-infiltrating WT1-specific CD4+ T cells, intratumoral CD4+ T cells from WT1 peptide vaccine-treated mice were stimulated with WT135–52 helper peptide and their IFN-γ and TNF-α production was measured." (PMID 34355173, 2021).
tumor (continued). "Moreover, this novel combination was found to induce notable HAGE- and WT1-specific T cells in the tumour bearing mice which were culled later in the experiment." (PMID 34262856, 2021). "A concordant increase in WT1 score was found with increasing tumor grade (p=0.013)." (PMID 32856872, 2020). "Based on encouraging evidence (albeit from small studies) showing measurable WT1-specific anti-tumor CD8+ T cell responses, a WT1 peptide vaccine using Montanide and GM-CSF as adjuvants is currently being explored in a phase I study in patients with recurrent OC who are in second or later remission." (PMID 33322601, 2020). "Autologous tumor lysate or peptide antigens (WT1, MUC1, CEA) according to the HLA-A pattern." (PMID 33679709, 2020). "However, the expression of Calretinin, WT-1 and Ki-67 in tumor tissue of the patient were stronger than that in the models." (PMID 33365269, 2020). "WT1 score increased proportionately with tumor grade (p=0.013)." (PMID 32856872, 2020). "Microscopically, the tumor cells were strongly positive for Desmin, Cyclin D1 and WT1, moderately positive for ER/PR, weakly positive for SMA (smooth muscle actin) and negative for CD 10, and the expert pathologist concluded it was “ESS with smooth muscle cells differentiation”." (PMID 32933053, 2020). "We subcutaneously inoculated an HLA-A∗24:02+WT1+ PDX tumor and an HLA-A∗24:02+WT1− one, the former expressing WT1 antigen at a moderate level and the latter expressing no WT1 antigen as a specificity control, into the right side and left side, respectively, on the back of a NOG mouse." (PMID 32259478, 2020). "Next we evaluated whether SUVmax of WT1-vaccinated skin reflect the magnitude of anti-tumor immune response." (PMID 32991475, 2020). "Two of these had mutations in WT1 and in one case the WT1 mutation was heterozygous, suggesting that the cells were not pure tumor cells." (PMID 33379206, 2020). "WT1 stained the cytoplasm, astrocytic processes and fibrillary tumor matrix." (PMID 32856872, 2020). "WT1 is also reported to regulate tumor angiogenesis via direct transactivation of ETS1." (PMID 32855630, 2020). "Once a homozygous WT1 mutation is present, the cells may be independent for an additional CTNNB1 mutation and could be the seeds for tumor development." (PMID 33379206, 2020). "WT1 may promote cell proliferation and participate in tumor cell infiltration and metastasis by regulating the transcriptional expression of growth factor genes." (PMID 32210734, 2020). "A putative relation between EGFR/KRAS mutation and the promoter methylation of CDH1, CDKN2Ap16, RASSF1A, TERT, and WT1 could influence tumor progression and therapy response." (PMID 32605217, 2020). "In agreement with this is the fact that the WT1 mutant Wilms8 tumor and cell culture has no additional pathogenic mutation except for CTNNB1." (PMID 33379206, 2020). "Also, the average tumour weight reduced 45% in mice transplanted with PANC‐1‐sh‐WT1#1 than that in control mice." (PMID 31845546, 2020). "Moreover, the strong WT1 expression in gemistocytic, anaplastic and large multinucleated tumor cells has been observed in one study." (PMID 32856872, 2020). "The administration of tumor vaccine enabled tumor control at lower CAR-T cell doses.Similar results have been shown in other studies using WT1-specific CAR-T cells combined with DC vaccine pulsed with WT1236Y peptide and CMV/CD19 bispecific T cells combined with CMV peptide vaccine." (PMID 33614478, 2020). "Likewise, WT1 score was observed to differ significantly according to tumor histopathology (p=0.02)." (PMID 32856872, 2020). "Analogous to the previous example, the affinity-matured HLA-A2/WT1 TCR-like mAb Q2L (scFv-hIgG1 Fc fusion) also exhibited improved cytotoxic capacity in in vitro ADCC assays as well as significantly reducing tumor burden in xenografted DKO mice compared to the mother clone." (PMID 31544838, 2019).
tumor (continued). "Therefore, we determined VEGF isoforms, Wt1, Srpk1, and Srsf1 expression in normal and tumor endothelial cells." (PMID 30641926, 2019). "Interestingly, an in vitro culture assay used to assess specific autologous tumor recognition revealed that the ESK1-BiTE induced a polyclonal activation of patient T cells against non-WT1 tumor epitopes." (PMID 31544838, 2019). "This proof-of-concept extended previous in vitro CAR studies targeting WT1-presenting tumor cells." (PMID 31544838, 2019). "The detection and generation of tumor-specific T cells from peripheral blood of healthy donors is feasible, but the ability to expand these cells in vitro is limited due to the low frequency of memory precursor WT1-specific T cells present in healthy donors." (PMID 30678050, 2019). "Inhibition of Srpk1 and Srsf1, and alterations in Vegf splicing, which induce tumor endothelial cell apoptosis, might contribute to the antitumor activity upon targeting Wt1." (PMID 30641926, 2019). "We analyzed VEGF isoforms, Wt1, Srpk1, and Srsf1 in normal and tumor endothelium." (PMID 30641926, 2019). "Similarly to the ESK1-BiTE, the ESK1 CAR (denoted WT1-28z CAR) was also able to kill tumor cells and enhance survival of mice, in particular with co-expression of IL-12." (PMID 31544838, 2019). "As the extension of this study, we also reported that bacillus Calmette-Guérin cell wall skeleton (BCG-CWS) and interferon-β, which were used as adjuvants, could enhance the anti-tumor effect of WT1 CTL peptide vaccine." (PMID 30542516, 2018). "As alluded to above, fusion of EWSR1 to WT1 in this pediatric malignancy abrogates the tumor suppressor role of WT1 as well as the RNA-binding capacity of EWSR1, and generates an oncogenic molecule capable of binding and transactivating WT1 target genes, including the IGF1R promoter." (PMID 29455671, 2018). "In addition, the percentage of vessels expressing Wt1 was greater in the tumours than control tissue of FVB mice." (PMID 30374123, 2018). "Next, we analyzed the enrichment of H3K27me3 and Ezh2 at the promoters of NGFR, WT1 and MME in these cell lines and human NSCs, and observed that H3K27me3 and Ezh2 were enriched at the promoters of WT1 promoter more than other two gene promoters in all these tumor lines tested." (PMID 29932419, 2018). "Moreover, WT1 is a tumour suppressor gene and is related to the distant metastasis and progression of tumour cells by its function as a master regulator of the mesenchymal-epithelial transition and epithelial-mesenchymal transition." (PMID 30266964, 2018). "ER status was available for 55 cancers; these cases were analysed to ascertain whether any difference in WT1 expression could be detected between ER-positive (n = 32) and ER-negative tumours (n = 23)." (PMID 30374123, 2018). "Moreover, TSGs such as WT1 are likely expressed in tumor-initiating cells, and consequently, contain low levels of H3K27me3 at their gene promoters." (PMID 29932419, 2018). "The authors hypothesize this cytotoxic response is a re-activation of pre-existing T-cells targeting the HER2/Neu antigen due to the close proximity facilitated by binding of ESK1-BiTE to WT1 on the tumor and CD3 on the T-cell." (PMID 30713535, 2018). "In addition, epithelial cells lining the TDLU in health and disease, alongside the tumour stromal cells, were also positive for WT1." (PMID 30374123, 2018). "WT1 is a transcription factor that acts as both a tumor suppressor and an oncogene." (PMID 30226466, 2018).
tumor (continued). "The liposome-WT1-shRNA-Tf reduced 34% of tumor weight in comparison to control group." (PMID 29861465, 2018). "Our group had already established a mouse WT1 immunotherapy model in which vaccination of mice with a WT1 CTL peptide (WT1126–134) could reject tumor transplanted in the mice." (PMID 30542516, 2018). "Furthermore, T-cell receptor repertoire analysis showed the oligoclonality of these tumor infiltrating WT1 tetramer+ CD8+ T cells, and 3 clones occupied about half of them." (PMID 30542516, 2018). "For example, the approach for targeting the WT1-peptide vaccine in ER-negative tumours may need to differ significantly compared to the approach taken with tumours which are ER-positive." (PMID 30374123, 2018). "Our patient does not have a deletion of 11p13 associated with a defect in WT1, the Wilms' tumor suppressor gene." (PMID 30123603, 2018). "Interestingly, the percentage of WT1-positive vessels within the tumours also decreased as tumour grade increased." (PMID 30374123, 2018). "Furthermore, the discovery that WT1 cooperates with TET2 to upregulate MEG3 expression places TET2-WT1-MEG3 signaling axis as a central tumor suppressive pathway in AML, therefore emphasizing the potentials of this axis in AML diagnosis and therapy." (PMID 28400619, 2017). "Therefore, expression in blastemal-predominant tumours would be expected to be higher than in triphasic or epithelial-predominant or stromal (WT1-mutant) tumours where the aggregating blastemal cells would express lower levels of FOXD1." (PMID 29040332, 2017). "Also, WT1 expression is significantly higher in ER-positive (luminal) than in ER-negative (basal) tumours." (PMID 28345629, 2017). "Furthermore, restricting the samples to those in which WT1 was detected, WT1 expression was significantly higher in ER-positive than in ER-negative tumours (p = 1.2e-5)." (PMID 28345629, 2017). "WT1 was significantly overexpressed in HCC tissue in compared with non-tumour liver." (PMID 29285297, 2017). "In addition the limited potential for muscle/ osteogenic/ adipogenic differentiation similar to all other WT1 mutant cell lines is also observed in the Wilms10 tumor cell line and this is retained in the immortalized cells." (PMID 27213811, 2016). "Indeed, it has been observed that WT1 can act as a tumor suppressor gene or, in some cases, as oncogene by considering the tumor histotype." (PMID 27014421, 2016). "The increased rate of relapse was more pronounced in children with abnormally low WT-1 gene expression, and may be explained by the tumor suppressor effect of WT1 gene." (PMID 26740869, 2016). "Finally, IHC staining indicated that the expression of WT1 was decreased while E-cadherin was increased in tumor xenograft from mice inoculated with A549-miR-193a than that inoculated with A549-miR-NC." (PMID 27821145, 2016). "WT1 seems to act as tumor suppressor gene in NB, by inducing the maturation of this tumor." (PMID 27014421, 2016). "Other known tumor suppressors such as WT1, CEBPA or CDKN1A are instead missed by our analysis." (PMID 26860319, 2016). "Wilms’ tumor 1 (WT1)-pulsed DC vaccine could improve neurological findings and shrink the tumor in a recent study." (PMID 26973839, 2016).